RN7SL188P (RNA, 7SL, cytoplasmic 188, pseudogene)
Gene: Miscellaneous RNA gene on chromosome 11 (16,576,851 to 16,577,135, forward strand). Ensembl gene ENSG00000241943.
Homologues: Orthologues: chimpanzee Metazoa_SRP (99% identical), macaque Metazoa_SRP (86% identical), rabbit Metazoa_SRP (69% identical), rat Metazoa_SRP (66% identical), guinea pig Metazoa_SRP (66% identical), rat Metazoa_SRP (65% identical), guinea pig Metazoa_SRP (64% identical). Paralogues in human: RN7SL2 (76% identical), RN7SL1 (75% identical), RN7SL650P (75% identical), RN7SL4P (75% identical), RN7SL3 (74% identical), RN7SL408P (74% identical), RN7SL444P (74% identical), RN7SL220P (74% identical), RN7SL18P (74% identical), RN7SL60P (73% identical), RN7SL448P (73% identical), RN7SL680P (73% identical), and 703 more.